CXCL14 (C-X-C motif chemokine ligand 14)
Diseases named in the same sentence as CXCL14 in open-access papers (continued):
Sharing a sentence is not in itself a finding about the gene and the disease.
ovarian carcinoma (19 papers, 2016 to 2025). A malignant neoplasm originating from the surface ovarian epithelium. "In ovarian cancer patients, abnormal overexpression of CXCL14 in serum and ovarian tissues is associated with poor prognosis, making it a novel auxiliary marker for early diagnosis of ovarian cancer." (PMID 39680618, 2024). "Stromal overexpression of CXCL14 in ovarian cancer was linked to poor patient survival via STAT3-dependent manner due to increased tumor cell proliferation." (PMID 36868311, 2023). "A previous study shown that LINC00092, activated by CXCL14-rich CAFs, drives ovarian cancer metastasis by modulating glycolysis via PFKFB2 interaction, underscoring a vital metabolic feedback loop between CAFs and cancer cell advancement." (PMID 39988592, 2025). "The secretion of CXCL-14 by CAFs upregulates LINC00092 in ovarian cancer, thereby promoting its glycolytic activity." (PMID 39717771, 2024). "The secretion of CXCL-14 by CAFs elevates the expression of LINC00092 in ovarian cancer cells, which in turn stabilizes PFKFB2 expression, propelling tumor glycolysis." (PMID 39717771, 2024). "For instance, CXCL-14 secreted by CAFs upregulates LINC00092 in ovarian cancer, and Midkine upregulates ST7-AS1 in gastric cancer." (PMID 39717771, 2024). "According to lncRNA microarray analysis (GEO accession number: GSE82059), LINC00092 is among the top five most upregulated lncRNAs treated with recombinant CXCL14 protein in ovarian cancer cells." (PMID 35842651, 2022). "The study aimed to investigate the potentiality of chemokines, including MCP-1, CCL15, CCL20, and CXCL14, as biomarkers for differential diagnosis between benign tumors and ovarian cancer (OC)." (PMID 36387204, 2022). "This study highlights a reciprocal feedback loop mediated by LINC00092 between CXCL14-positive CAFs and ovarian cancer cells that is crucial for promoting the metastatic behavior of ovarian cancer." (PMID 35842651, 2022). "The transcriptional levels of CXCL1, CXCL8, CXCL10, CXCL11, CXCL12, CXCL13, and CXCL14 were significantly elevated while CXCL3 was obviously reduced in ovarian cancer vs normal ovarian tissue." (PMID 33763130, 2021). "Researchers also found that upregulated CXCL14 and CXCL16 were associated with poor survival outcomes and promoted ovarian cancer cells proliferation." (PMID 33763130, 2021). "Using lncRNA microarrays, it was found that LINC00092 was one of the lncRNAs upregulated in ovarian cancer cells after CXCL14 treatment." (PMID 33050576, 2020). "CXCL14 is highly expressed in tumor stroma compared with normal stroma and is negatively correlated with the overall survival of patients with ovarian cancer." (PMID 33050576, 2020). "In ovarian cancer, CXCL14 regulated LINC00092 which bound glycolytic enzyme fructose-2,6-biphosphatase (PFKFB2) to promote its metastasis." (PMID 33204328, 2020). "In return, tumor cells also secreted exosomes including LncRNA-CAF to stroma and increased LncRNA-CAF levels for the activation of CAFs.In addition, LINC00092 was found to be upregulated in response to the CAF-secreted chemokine CXCL14 in ovarian cancer cells." (PMID 31448238, 2019). "CAFs-secreted CXCL14 induces LINC00092 upregulation which promotes ovarian cancer metastasis by enhancing PFKFB-2 translation." (PMID 31448238, 2019). "CXCL14 was highly expressed in advanced ovarian-cancer patients and correlated with poor prognosis." (PMID 36012586, 2022). "Further investigation showed that CXCL14 (C-X-C motif chemokine ligand 14) derived from CAFs could increase the expression of LINC00092 in ovarian cancer cells." (PMID 33520725, 2020). "CXCL14 was exclusively identified in fibroblasts, whereas its corresponding receptor, CXCR4, was found in fibroblasts, ovarian cancer cells, and plasma cells." (PMID 39135097, 2024).
ovarian carcinoma (continued). "Interestingly, the high expression of CXCL14, a powerful angiostatic chemokine that inhibits angiogenesis, is correlated with good progression-free survival in endometrioid ovarian cancer and is expressed in normal tissues such as epithelia and ovarian cancer stroma." (PMID 39135097, 2024). "CXCL14 is known to mediate CAF-induced pro-tumorigenic effects (migration, invasion, and metastasis) in ovarian cancer." (PMID 33050576, 2020). "In addition, CXC-chemokine ligand 14 (CXCL14), which is secreted by CAFs, stimulates the expression of LINC00092 in ovarian cancer cells." (PMID 35842651, 2022).
Obesity (18 papers, 2010 to 2025). Accumulation of substantial excess body fat. "CXCL14, on the other hand, has been negatively associated with obesity and type 2 diabetes, further strengthening the differences among these two chemokines in metabolic homeostasis." (PMID 39848402, 2025). "CXCL14 counteracts metabolic disorders and insulin resistance associated with obesity by stimulating brown adipose tissue activity, promoting browning of white adipose tissue, and recruiting M2-type macrophages." (PMID 39334887, 2024). "CXCL14-deficient mice can survive and reproduce with some degree of immune deficiency, but they appear to have a protective effect against obesity-induced insulin resistance." (PMID 37835681, 2023). "We recently reported that CXCL14-deficient (CXCL14−/−) female mice in the mixed background are protected from obesity-induced hyperglycemia and insulin resistance." (PMID 20428232, 2010). "Taken together, these data show that the lower body weight resulting from CXCL14 deficiency moderates obesity caused by genetic hyperphagia and reduced energy expenditure." (PMID 20428232, 2010). "Obesity, and especially comorbid T2DM, have been associated with abnormally low blood CXCL14 levels and impaired CXCL14 expression in adipose tissue." (PMID 39275140, 2024). "C-X-C Motif Chemokine Ligand 14 (CXCL14), a dendritic recruiter that is activated in specific circumstances such as obesity and insulin resistance, is another possibility that can explain this behavior." (PMID 35399507, 2022). "Abrogation of the signal pathways of CXCL14, CXCL5, CCL2, or their cognate chemokine receptors, alleviated obesity-associated metabolic abnormalities in high fat diet (HFD)-induced obese mice." (PMID 34948325, 2021). "In their study, thermogenic stimuli led to the increase in CXCL14 levels and also the release of CXCL14 by BAT, which exhibits potential beneficial effects to obesity-associated metabolic diseases such as metabolic syndrome and type 2 diabetes." (PMID 34948325, 2021). "Several recently discovered batokines, such as FGF21, NRG4, BMP8b, CXCL14, or adiponectin have been shown to exert a protective role against obesity by enhancing beiging of WAT, lipolysis, sympathetic innervation, or polarization of M2 macrophages." (PMID 34708041, 2021). "In this study, we present evidence that CXCL14 indirectly regulates food intake and is required for body weight gain in two genetic mouse models of obesity, ob/ob and Ay mice." (PMID 20428232, 2010). "Furthermore, levels of CXCL14 in plasma and expression in adipose tissue are abnormally downregulated in obesity and T2DM." (PMID 41187617, 2025). "FAP2 cells demonstrated enhanced expression of the genes encoding DPP4 (Dpp4), an adipose stem cell marker that also identifies Cxcl14-negative FAPs, and endosialin (Cd248), an obesity-associated glycoprotein." (PMID 38954467, 2024). "Growing evidence suggests that CXCL14 is closely related to obesity-induced insulin resistance." (PMID 37835681, 2023). "CXCL14 was found to be a new biomarker for obesity, type-2 diabetes and liver fibrosis." (PMID 35468838, 2022). "In addition, overexpression of CXCL14 in skeletal muscle restored obesity-induced insulin resistance in CXCL14−/− mice." (PMID 34948325, 2021). "Interestingly, overexpression of CXCL14 in skeletal muscle restored obesity-induced insulin resistance in Cxcl14−/− mice, suggesting that CXCL14 is important during glucose uptake in skeletal muscle and by doing so this chemokine regulates glucose metabolism." (PMID 24741577, 2014). "Finally, here we presented evidence demonstrating that disruption of CXCL14 results in reduced body weight using two representative genetic mouse models of obesity." (PMID 20428232, 2010). "This review provides an in-depth analysis of specific chemokines involved in the development of obesity, including C-C motif chemokine ligand 2 (CCL2), CCL3, CCL5, CCL7, C-X-C motif chemokine ligand 8 (CXCL8), CXCL9, CXCL10, CXCL14, and XCL1 (lymphotactin)." (PMID 39334887, 2024).
Obesity (continued). "CXCL-14 supports the immune system, but in the metabolic context, the role of CXCL-14 in obesity is complicated." (PMID 36145221, 2022). "Regarding the circulating markers of BAT activity, CXCL14, secretin, and 12,13-dihydroxy-9Z-octadecenoic acid (12,13 di-HOME) were similar in the two groups, whereas there was a trend for higher FGF21 in the subjects overweight/obesity." (PMID 35928901, 2022). "It is of note that the blood insulin levels of CXCL14−/− female mice are lower than those of control female mice irrespective of obesity." (PMID 20428232, 2010).
melanoma (12 papers, 2012 to 2024). A malignant, usually aggressive tumor composed of atypical, neoplastic melanocytes. "As an example, two adjacent guanine to adenine mutations in a patient with melanoma can disrupt one of the five G-runs in the 5′ UTR of CXCL14 and destabilise the predicted RNA G4." (PMID 28386116, 2017). "Treatment of Wt and Tg mice with α-galactosyl ceramide, which stimulates NKT cell function, synergistically suppressed metastasis of melanoma cells with CXCL14." (PMID 31014014, 2019). "To investigate the effects of overexpression of CXCL14 on the life span of mice, we used the Kaplan-Meir method to determine the survival rates after injection of various numbers of B16 melanoma cells." (PMID 31014014, 2019). "The importance of NK cells on the metastasis was also supported when CXCL14 was expressed in B16 melanoma cells." (PMID 25765541, 2015). "Further, these CXCL14-overexpressing mice were subsequently injected with B16 melanoma or LLC cells in order to show the effects of high-level CXCL14 expression on the tumour growth and metastasis of these cell types." (PMID 25765541, 2015). "The injection of this antibody also attenuated the suppressive effects of CXCL14 on tumour volume in the Tg mice, resulting in more pronounced increases of 13- and 11-fold for the melanoma and LLC cells, respectively." (PMID 25765541, 2015). "We also produced CXCL14-expressing B16 melanoma cells under the control of Dox (B16-luc2Tet/OnBRAK)." (PMID 25765541, 2015). "In order to examine the effects of CXCL14 expression in the tumour cells on the rate of metastasis, we produced B16 melanoma cells that expressed the CXCL14 genes under the control of doxycycline (Dox)." (PMID 25765541, 2015). "CXCL14 transgenic mice injected with Lewis Lung Carcinoma (LLC) or B16 melanoma cells showed a reduced tumor growth and interestingly, CXCL14 transgenic mice injected with LLC showed a decrease in the number and diameters of visible blood vessels in tumors in comparison to WT mice." (PMID 35626056, 2022). "To find the actual effects of CXCL14 on metastasis in transgenic mice, we employed an experimental metastasis system and found that for both melanoma cells and LLC cells, the number of nodules in the lungs of the transgenic mice was significantly lower than that observed for the wild-type animals." (PMID 31014014, 2019). "These Tg mice show suppressed growth of Lewis lung carcinoma (LLC) cell and B16 melanoma cell-transplants, indicating CXCL14/BRAK, first found as a tumor progression suppressor for HNSCC, also suppresses the progression of tumors of other tissue origins by a paracrine or endocrine mechanism." (PMID 23762619, 2012). "We could not detect expression of mouse CXCL14/BRAK gene in either LLC or melanoma cells by RT-PCR, indicating that CXCL14/BRAK produced by the Tg mice functions in a paracrine and/or endocrine fashion." (PMID 23762619, 2012). "For other chemokines, most of them tended to express higher in FGFR Mut melanoma, such as CCL5, CCL19, CXCL9, CXCL10, CXCL11, CXCL13 and CXCL14 (all P > 0.05)." (PMID 36426352, 2022). "In the turquoise module, the hub genes Cxcl14 and Slit3 are known to inhibit EMT by suppressing respectively the NF-κB and Robo signaling pathways; they were shown to reduce cell migration in melanoma." (PMID 32831131, 2020). "The growth of transplanted B16 melanoma cells and LLC cells was also suppressed in transgenic mice compared with that in wild-type mice, indicating that CXCL14 suppressed both carcinogenesis and tumor growth." (PMID 31014014, 2019). "In conclusion, our data indicate that CXCL14/BRAK Tg has suppressed growth of LLC and B16 melanoma cell transplants." (PMID 23762619, 2012).
pancreatic cancer (12 papers, 2009 to 2024). "CXCL14 did increase the migratory capacity of pancreatic cancer cells in a trans-well in vitro assay, suggesting a role in increasing the invasive capabilities of cancer cells." (PMID 38339310, 2024). "In contrast to the distribution pattern in other normal and cancerous tissues, CXCL14 is upregulated in pancreatic cancer tissues compared to chronic pancreatitis and normal pancreas." (PMID 31561620, 2019). "On the other hand heightened CXCL14/BRAK expression has been reported to occur in adenocarcinomas such as prostate and breast cancers and in pancreatic cancer cells." (PMID 23762619, 2012). "Although CXCL14 suppresses tumor growth in some type of cancer, CXCL14 is involved in invasion of pancreatic cancer." (PMID 19521519, 2009). "Five mRNAs were shared between the two datasets, with SLC3A1 and IAPP down-regulated whereas CXCL14, ANLN, and TPRS1 up-regulated in pancreatic cancer." (PMID 33925948, 2021). "Other members of the C-X-C motif chemokine family were found to be upregulated in pancreatic cancer cells after Rintatolimod treatment, like CXCL 1, CXCL2, CXCL3, CXCL8 (IL-8), CXCL11, CXCL14, and CXCL16." (PMID 34207861, 2021). "CXCL14 is increased in the invasive front of PDAC specimens, and treatment with CXCL14 significantly increases the invasiveness of pancreatic cancer cells, suggesting that CXCL14 may function as an oncogene in PDAC." (PMID 39358777, 2024). "In contrast, the authors were able to show that CXCL14 increased invasiveness of pancreatic cancer cells by influencing the RelA subunit without affecting MMP-2 and VEGF secretion." (PMID 31561620, 2019). "Furthermore, the treatment of pancreatic cancer cells with recombinant CXCL14 did not increase cell proliferation nor did CXCL14 protect against gemcitabine-induced apoptosis when cells were treated with the IC50 concentration of gemcitabine in vitro." (PMID 38339310, 2024).
glioma (11 papers, 2011 to 2024). A benign or malignant brain and spinal cord tumor that arises from glial cells (astrocytes, oligodendrocytes, ependymal cells). "Another lncRNA, urothelial carcinoma-associated 1 (UCA1), was also reported to be induced in glioma cells by paracrine CXCL14 secretion from glioblastoma-associated stromal cells." (PMID 33050576, 2020). "Overall, the UCA1/miR-182/PFKFB2 axis is associated with chemokine CXCL14 secretion, glycolysis, and invasion of glioma cells in GASCs." (PMID 31014014, 2019). "The chemokine CXCL14 modulates GBM-associated stromal cells, modifies the immune microenvironment, and enhances the invasiveness of glioma cells." (PMID 39534094, 2024). "CXCL14 was expressed mainly by a diverse group of glioma cells, while CCL20, in contrast, was mainly expressed by myeloid cells and T lymphocytes." (PMID 39272976, 2024). "In this work, CXCL9, CXCL10, and CXCL14 were also identified as potential vital regulators of glioma progression among the CXCL family." (PMID 34603309, 2021). "They found that CXCL14 expression was negatively correlated with OS in patients with glioma in the TCGA dataset." (PMID 32942567, 2020). "The long non-coding(lnc) RNA UCA1/micro RNA (miR)-182 axis has been regarded as a nodal driver of glioma invasion mediated by GB-associated stromal cells (GASCs) and GASC-secreted chemokine CXCL14." (PMID 31014014, 2019). "In the Rembrandt dataset, including 315 gliomas of different grades, the highest CXCL14 expression is found in grade IV tumors, the most aggressive and lethal ones." (PMID 31117166, 2019). "CXCL9, CXCL10, CXCL11, CXCL12, and CXCL14 were filtered as main contributors of glioma progression." (PMID 34603309, 2021). "Force-mediated ECM remodeling through CCL2/JAK1/MLC2 signaling and the secretion of CXCL14 and C5a may be drivers of the glioma invasion mediated by GASCs." (PMID 32942567, 2020). "Interestingly, GASCs expressing high levels of CXCL14 have been shown to upregulate lncRNA UCA1 and downregulate miR-182, with miR-182 directly binding to PFKFB2 to modulate CXCL14 secretion, glycolysis, and the invasion of glioma cells." (PMID 30234009, 2018). "Similarly, the long non-coding RNA UCA1/miR-182 has been observed to be a nodal driver of metastasis in glioma that is mediated by glioblastoma-associated stromal cells (GASCs) and the GASC-secreted chemokine CXCL14." (PMID 30234009, 2018). "This last observation in particular may overlap with that, by Zeng and co-authors, about a trend of CXCL14 overexpression in IDH wt gliomas vs IDH mutant ones: G-CIMP tumors in fact were closely related to IDH mutation, and a better prognosis characterizes patients carrying them." (PMID 31117166, 2019). "In the training cohort, CXCL14 (P value < 0.001), CXCL9 (P value < 0.05), CXCL10 (P value < 0.001), CXCL11 (P value < 0.001), CXCL6 (P value < 0.001), and CXCL1 (P value < 0.001) were enriched in the IDH wide-type gliomas." (PMID 34603309, 2021). "Notably, CXCL14-high GASCs mediated lncRNA UCA1 upregulation and miR-182 downregulation in glioma cells." (PMID 31014014, 2019).
head and neck squamous cell carcinoma (11 papers, 2012 to 2025). A squamous cell carcinoma that arises from any of the following anatomic sites: lip and oral cavity, nasal cavity, paranasal sinuses, pharynx, larynx, and salivary glands. "Reactive oxygen species (ROS) reduce the expression of BRAK/CXCL14 in human head and neck squamous cell carcinoma cells." (PMID 37469162, 2024). "In head and neck squamous cell carcinoma (HNSCC), CXCL14 expression and secretion and its anti-tumor effect is negatively regulated by RhoA/ROCK pathway." (PMID 26733763, 2016). "In head and neck squamous cell carcinoma (HNSCC) cells, EGF has been shown to function as an upstream factor of CXCL14, and the EGFR tyrosine kinase inhibitor can restore CXCL14." (PMID 34696665, 2021). "Another study also confirms that CDX2/p300 enhances NK cell-mediated immunotherapy against head and neck squamous cell carcinoma in vitro; the findings indicate that CDX2 stimulated NK cell migration, cytotoxicity and infiltration by upregulating CXCL14 in HNSCC tissues." (PMID 36980527, 2023). "In head and neck squamous cell carcinoma (HNSCC), CXCL14 could be used as a functional prognosis biomarker for patients’ better overall survival rate." (PMID 34744744, 2021). "We have previously shown that CXCL14 expression is epigenetically downregulated in human papillomavirus-positive (HPV+) head and neck squamous cell carcinoma (HNSCC) and cervical cancer (CxCa)." (PMID 38400076, 2024).